LRRK2 (leucine rich repeat kinase 2)
Diseases named in the same sentence as LRRK2 in open-access papers (continued):
Sharing a sentence is not in itself a finding about the gene and the disease.
colitis (continued). "This severe colitis in Ncf1* mice was mediated by increased local production of peroxynitrites, pro-inflammatory cytokines and phosphorylated LRRK2." (PMID 24873968, 2014). "To unravel the mechanisms underlying the increased tumor promotion and progression observed in LRRK2 KI mice, we hypothesized that this mutation could enhance the susceptibility to DSS-induced colitis, thus promoting cancer pathogenesis." (PMID 38607004, 2024). "Therefore, we determined the status of inflammasome activation in colon tissues from LRRK2 KI mice and WT controls after colitis induction." (PMID 38607004, 2024). "In addition, LRRK2 KI mice manifested more exacerbated colitis symptoms including a shortened colon length and increased spleen weight when compared with those in WT mice." (PMID 38607004, 2024). "Markedly, both inhibitors attenuated DSS-induced colitis in LRRK2 KI mice." (PMID 38607004, 2024). "Furthermore, the inhibition of the kinase activity of LRRK2 mitigated colitis severity in both KI mice and WT controls, underscoring the crucial role of LRRK2 kinase activity in intestinal inflammation." (PMID 38607004, 2024). "Furthermore, partial pharmacological inhibition of LRRK2 kinase activity also reduced the colitis phenotype and inflammation." (PMID 37289222, 2023). "Next, to shed light into the link between IBD and PD we induced colitis in a LRRK2-PD mouse model." (PMID 37289222, 2023). "Although a higher inhibition of LRRK2 might be necessary to achieve full rescue, our results indicate that pharmacological inhibition of LRRK2 can be protective against colitis." (PMID 37289222, 2023). "In a mouse model of colitis induced by dextran sodium sulfate, LRRK2 lies downstream of the β-glucan receptor Dectin-1 and overexpression of LRRK2 leads to the activation of the NF-κB components, TAK1 complex and TRAF6, and the enhancement of pro-inflammatory cytokine secretion." (PMID 36972292, 2023). "Importantly, our results show that pharmacological inhibition of LRRK2 kinase activity rescues the exacerbated colitis phenotype." (PMID 37289222, 2023). "The bone marrow transplantation experiment confirmed our hypothesis, since substitution of the GS LRRK2 mice immune cells with WT cells could rescue the colitis disease phenotype and reduce the inflammation in the colon." (PMID 37289222, 2023). "To date, few studies have been published examining colitis in LRRK2 genetic mouse models." (PMID 33750819, 2021). "While the mechanism by which LRRK2 alters inflammation in the context of colitis models is still being explored, additional studies have suggested other hypotheses related to LRRK2 expression and its kinase activity in the gut." (PMID 33750819, 2021). "Among the alleles in the LRRK2 gene locus, the risk allele at rs11564258 located downstream of LRRK2 has the highest risk polymorphism for IBD and heterozygote animal cases exhibited increased severity of colitis." (PMID 34593025, 2021). "Furthermore, genetic association studies have suggested that LRRK2/MUC19 and ATG7 deficiency aggravate intestinal inflammation in a mouse model of colitis." (PMID 30669622, 2019). "In a recent study, both lymphoblastoid cells from control patients bearing a high-risk allele of LRRK2 and dendritic cells from CD patients exhibited elevated LRRK2 expression, which resulted in severe colitis with increased Dectin-1-mediated NF-κB activation and proinflammatory cytokine responses." (PMID 30669622, 2019). "Given that Lrrk2 KO mice show vulnerability to experimentally induced colitis as well as to intestinal infection, LRRK2 might play an important role in maintaining the innate immune system active in peripheral tissues." (PMID 32714591, 2018). "Furthermore, an analysis of experimental colitis in LRRK2 KO animals revealed exacerbated disease severity compared with normal animals." (PMID 28099919, 2017).
colitis (continued). "Unlike the observation with experimental colitis, mice deficient in Lrrk2 were found in our study to be less susceptible than the WT controls to the induction of EAU." (PMID 26067490, 2015). "LRRK2 is a potent negative regulator of the nuclear factor of activated T cells (NFAT), and earlier studies have shown that the lack of LRRK2 negatively regulates the activation of the transcription factor NFAT, leading to increased susceptibility to DSS-induced colitis in mouse models." (PMID 40842999, 2025). "Finally, we demonstrated that genetic targeting of specific LRRK2 substrates reduces colitis severity in Lrrk2N2081D mutation carriers, whereas a small molecule LRRK2 inhibitor did not produce a clear therapeutic effect." (PMID 41031878, 2025). "Notably, GSDMD inhibitors attenuate colitis in LRRK2 G2019S KI mice." (PMID 38607004, 2024). "To test this hypothesis, we induced colitis in both WT and LRRK2 KI mice." (PMID 38607004, 2024). "Therefore, we hypothesized that GSDMD inhibitor treatment in LRRK2 G2019S KI mice will reduce DSS-induced colitis." (PMID 38607004, 2024). "In total, these findings suggest that LRRK2 kinase activity plays a crucial role in the development of DSS-induced colitis, which indicates that targeting LRRK2 kinase activity provides a potential method for inhibiting the development of colitis and colitis-associated cancer." (PMID 38607004, 2024). "In this study, we first established a chronic and progressive colitis model by administration of increasing concentrations of DSS during a period of 28 days and compared the response between knock-in mice carrying the G2019S LRRK2 mutation (GS LRRK2) and control wild-type mice (WT LRRK2)." (PMID 37289222, 2023). "However, in our experimental colitis model we did not detect loss of the dopaminergic neurons in the SN in the WT mice or in the GS LRRK2 mice, despite the observed neuroinflammatory changes." (PMID 37289222, 2023). "This indicates the clear involvement of LRRK2 kinase activity in immune cells and exacerbation of inflammatory phenotypes in G2019S mice during DSS-induced colitis." (PMID 40883285, 2025). "However, MLi-2 had minimal impact on body weight loss, spleen weight, and colon length, damage, and inflammation, suggesting that in-diet dosing of the LRRK2 kinase inhibitor MLi-2 does not provide significant protection from DSS-induced colitis in N2081D mutation carriers." (PMID 41031878, 2025). "Taken together, our data demonstrate that LRRK2 G2019S KI promotes inflammasome activation and necrosis in the context of DSS-induced colitis." (PMID 38607004, 2024). "Phosphorylation on S-1292 was significantly increased in GS LRRK2 mice, but to the same extent in control and DSS conditions, indicating that the kinase activity of LRRK2 remains unaltered during colitis." (PMID 37289222, 2023). "Severe colitis was mediated by increased local expression of cytokines (IL-6, IL-10, TNF-α, IFN-γ and IL-17A) and phosphorylation of Leucine-rich repeat kinase 2 (LRRK2)." (PMID 24873968, 2014). "A surprising finding in our study is that dietary administration of the LRRK2 kinase inhibitor MLi-2 did not significantly alleviate DSS-induced colitis in N2081D mice despite reducing RAB10 phosphorylation in colon tissue." (PMID 41031878, 2025). "To examine the potential role of LRRK2 kinase activity in DSS-induced colitis, we then investigated the impact of LRRK2-IN-1 treatment on colitis development in both LRRK2 KI mice and littermate controls using the DSS colitis model." (PMID 38607004, 2024). "In addition, both LRRK2 knock-out and BAC transgenic overexpression mice demonstrated enhanced vulnerability to DSS-induced colitis." (PMID 37289222, 2023). "Based on this model, to explore the role of LRRK2 and gut inflammation further, future research should investigate neurodegeneration and α-synuclein pathology in the ENS and the CNS of LRRK2 transgenic mice subjected to DSS-induced colitis." (PMID 32508566, 2020).
colitis (continued). "Finally, we show that knockout of Rab12, but not pharmacological LRRK2 kinase inhibition, significantly reduced colitis severity in Lrrk2N2081D mice." (PMID 41031878, 2025). "Studies examining LRRK2 in colitis models have been limited in scope and do not examine the effects of intestinal inflammation on PD-associated pathology in either the nigrostriatal pathway or the GI system as other studies have done in wildtype animal models detailed below." (PMID 33750819, 2021). "Furthermore, an elegant study by Liu and collaborators demonstrated that LRRK2 is a negative regulator of the Nuclear Factor of activated T-cells (NFAT) and observed that LRRK2−/− mice display abnormal sensitivity to experimentally induced colitis." (PMID 22594666, 2012).
neuroblastoma (36 papers, 2007 to 2025). Neuroblastoma (NB) is the most common solid, extracranial childhood tumor. "Human neuroblastoma SH-SY5Y cells stably expressing wildtype or pathogenic LRRK2 were used to test for polarity defects in the context of centrosomal positioning." (PMID 29357897, 2018). "To evaluate effects of pathogenic LRRK2 on cell polarity, we employed human neuroblastoma SH-SY5Y cells stably expressing flag-tagged wildtype or G2019S mutant LRRK2." (PMID 29357897, 2018). "We found that deficient LRRK2 signaling increased hαSyn- or 6-OHDA-mediated neuroblastoma cell death or nematode DAergic neuron degeneration." (PMID 21857923, 2011). "Primary cortical neurons from PD pathogenic LRRK2 R1441G KI mice display a greater rotenone-induced decrease in ATP levels, and neuroblastoma cells harboring the pathogenic G2019S LRRK2 mutation have decreased cellular ATP levels due to mitochondrial uncoupling." (PMID 40440058, 2025). "Moreover, we found that LRRK2 also is important for human neuroblastoma cell death mediated by tunicamycin, a chemical that causes accumulation of unfolded proteins by inhibiting protein glycosylation." (PMID 21857923, 2011). "This analysis extends our findings to human neurons expressing LRRK2 at endogenous levels and validates findings in neuroblastoma cells." (PMID 40279672, 2025). "But equally, activating TPC2 with TPC2-A1-P also reset deviant Ca2+ signals, both in neuroblastoma cells overexpressing LRRK2 G2019S and in iPSC-derived dopaminergic neurons expressing pathogenic LRRK2 at endogenous levels, as well as movement defects in vivo." (PMID 40279672, 2025). "This indicates that enhanced Rit2 expression counteracts pS129-aSyn accumulation not only in recombinant neuroblastoma cell lines, but importantly also in an in vivo PD mouse model, providing effective neuroprotection in a non-LRRK2 modeling paradigm." (PMID 36973269, 2023). "To assess the specificity of the α-synuclein-dependent ITPKB increase, we used SH-SY5Y neuroblastoma cells, in which LRRK2 or its most widespread mutant (G2019S) were expressed." (PMID 36768321, 2023). "Here we report that Rit2 reduces phosphorylation levels of S1292-LRRK2 in recombinant neuroblastoma cells and is neuroprotective in animals with no LRRK2 mutations, therefore we assessed the impact of Rit2 on S1292 autophosphorylation in the mouse DA neurons." (PMID 36973269, 2023). "Miro1 has direct interactions with certain proteins encoded by PD-linked genes such as PTEN-induced kinase 1 (PINK1), PARKIN and Leucine-rich repeat kinase 2 (LRRK2) (as witnessed in human neuroblastoma cells and D. melanogaster primary neurons)." (PMID 37150812, 2023). "In studies on murine primary neurons and human neuroblastoma, the interaction between endogenous LRRK2 and the fission regulator Drp1 increased Drp1 phosphorylation and mitochondrial fission." (PMID 35965315, 2022). "We found that transient expression of G2385R-LRRK2 significantly induced neurotoxicity in human neuroblastoma SH-SY5Y cells compared with vector cells alone or cells expressing wild-type (WT)-LRRK2." (PMID 34720999, 2021). "SH-SY5Y neuroblastoma cell lines were cotransfected with empty vector and mitochondrial-targeted aequorin (mtAEQ) Ca2+ probe (control) or G2019S Lrrk2 plasmid together with mtAEQ (G2019S KI)." (PMID 29434188, 2018). "We confirmed the ectopic expression of LRRK2 WT and its mutant variants in differentiated SH-SY5Y neuroblastoma cells." (PMID 30150626, 2018). "The expression of HOTAIR and LRRK2 were detected in the PD mice and in human neuroblastoma cell lines SH-SY5Y pretreated with MPP+." (PMID 28445933, 2017). "To further investigate the link between LRRK2 and the AP-3 complex in mammalian cells, we performed co-immunoprecipitation (IP) studies in transfected human neuroblastoma SH-SY5Y cells." (PMID 27424887, 2016).
neuroblastoma (continued). "Oxidative stress induced by LRRK2 was salvaged by DJ-1 in a neuroblastoma cell line, suggesting that antioxidants are potential inhibitors of LRRK2 kinase toxicity." (PMID 26988916, 2016). "Specifically, we found that LRRK2 supported GRP78 upregulation in human neuroblastoma cells exposed to 6-OHDA, and that GRP78/HSP-4 protected these cells and nematode DAergic neurons against the toxicity of 6-OHDA or hαSyn." (PMID 21857923, 2011). "Taken together, these data indicate that, as in nematodes, LRRK2 activates the p38 pathway in response to 6-OHDA exposure in human neuroblastoma cells." (PMID 21857923, 2011). "Here, we used C. elegans, human neuroblastoma cells and murine cortical neurons to determine the role of LRRK2 in maintaining dopaminergic neuron viability." (PMID 21857923, 2011). "In the work reported here, we investigated the molecular mechanism by which LRRK2 impacts the viability of DAergic neurons of C. elegans, a human neuroblastoma cell line and murine cortical neurons." (PMID 21857923, 2011). "Insufficient LRRK2 kinase activity resulted in more vulnerable nematode neurons and human neuroblastoma cells, possibly through p38 signaling." (PMID 21857923, 2011). "A proteomics study performed in neuroblastoma cells, either expressing LRRK2 and pharmacologically treated with an enzyme inhibitor or expressing the G2019S LRRK2 mutant, led to identifying 776 phosphorylation sites whose levels changed by +/- 50% upon inhibition of the enzyme." (PMID 31277513, 2019). "Furthermore, in a study performed in C. elegans and human neuroblastoma cells, it was shown that BiP/GRP78 expression depends on the leucine-rich repeat kinase 2 (LRRK2), the most commonly mutated protein in PD." (PMID 26923166, 2016). "In this report, we investigated whether LRRK2 alters neural transport using live-cell imaging techniques and human neuroblastoma SH-SY5Y cells." (PMID 28119604, 2016). "We found that LRRK2 acts to protect neuroblastoma cells and C. elegans dopaminergic neurons from the toxicity of 6-hydroxydopamine and/or human α-synuclein, possibly through the p38 pathway, by supporting upregulation of GRP78, a key cell survival molecule during ER stress." (PMID 21857923, 2011). "Since the ability of LRRK2 to protect nematode DAergic neurons and human neuroblastoma cells from 6-OHDA and hαSyn was found to involve p38 activation, we examined whether p38 was also involved in promotion of DAergic neuron degeneration by G2019S mutant LRRK2." (PMID 21857923, 2011). "Testing of XL01126 and cis-XL01126 on SH-SY5Y, a human neuroblastoma cell linewidely used as PD cell model, revealedthat XL01126 induced 50% or more degradation of LRRK2 after 6 h/300nM or 24 h/300 nM treatment." (PMID 36007011, 2022). "To probe for possible cell type-specific differences, we examined the effects of RAB7L1 expression in human SH-SY5Y neuroblastoma cells stably transduced with GFP, or with flag-tagged wildtype or G2019S mutant LRRK2, respectively." (PMID 30483055, 2018). "To further explore the functional role of LRRK2, we combined synaptopHluorin assay to TIRF microscopy (TIRFM) in the neuroblastoma cell line SH-SY5Y." (PMID 28710481, 2017). "It has been shown that LRRK2 interacts in vitro with PARKIN and the expression of mutant LRRK2 induced apoptotic cell death in neuroblastoma cells and in mouse cortical neurons." (PMID 29236052, 2017). "Also, we and other groups have demonstrated that neuroblastoma cell lines expressing I2020T LRRK2 are more susceptible to oxidative stress than those expressing wild-type LRRK2, although no consensus has been established regarding the molecular mechanism involved." (PMID 22534020, 2012).
neuroblastoma (continued). "Mouse neuroblastoma N2a cells pretreated with LRRK2, AP3B1, or non-targeting siRNA were surface-labeled with an Alexa488-conjugated antibody to the extracellular domain of LAMP1 for 30 min at 4 °C." (PMID 27424887, 2016). "The successful detection of LRRK2 Ser935 phosphorylation via TR-FRET in U-2 OS cells prompted us to test the feasibility of using difficult-to-transduce, but more relevant cell backgrounds such as neuroblastoma line SH-SY5Y and human neural stem cells (NSCs)." (PMID 22952710, 2012). "Following transient transfection of neuroblastoma SH-SY5Y cells, western blot analysis of cell lysates showed bands at the predicted molecular weight of each construct using anti-HA, anti-C-terminal-LRRK2 or anti-GFP antibody (not shown)." (PMID 23028814, 2012).